MET (MET proto-oncogene, receptor tyrosine kinase)
Diseases named in the same sentence as MET in open-access papers (continued):
Sharing a sentence is not in itself a finding about the gene and the disease.
breast carcinoma (continued). "Further studies are needed to examine the reaction of breast cancer cells, especially cancer stem cells, to NaBu and c-MET in the patient, since cancer stem cells are resident in and dynamically regulated by its specific micro-environment." (PMID 22253909, 2012). "A combination treatment of MET siRNA and NaBu administration can efficiently eliminate breast cancer." (PMID 22253909, 2012). "Our study clarified that the oncogene MET contributed to the NaBu- resistant effect of breast cancer cell." (PMID 22253909, 2012). "In the present study, we found that c-MET protects breast cancer cells from the apoptosis induced by NaBu." (PMID 22253909, 2012). "A combination treatment of MET siRNA and NaBu efficiently prohibited the breast cancer progression, and the incident rate of the tumor decrease to 18%." (PMID 22253909, 2012). "MET overexpression is observed in 20–30% of human breast cancers and is a strong, independent predictor of decreased survival." (PMID 21049054, 2010). "While the finding may not be considered conclusive due to the small sample size examined, this study suggests a potentially key role for c-MET in breast cancer metastasis." (PMID 40361420, 2025). "The second case showed metastatic lung adenocarcinoma with MET exon 14 deletion and metastatic breast adenocarcinoma involving different mediastinal lymph nodes, respectively, in a patient with a previous history of breast carcinoma." (PMID 40028792, 2025). "Moreover, a separate study revealed that among all breast cancers, the basal subtype was correlated with the highest levels of c-MET in tumor samples." (PMID 40361420, 2025). "For example, while FolTAC-dual effectively targets EGFR and HER2 in resistant HER2+ breast cancer, compensatory signaling through other tyrosine kinases or pathways, such as MET or IGF-1R, may emerge over time." (PMID 41038820, 2025). "Moreover, increased MUC5AC expression was observed in breast cancer brain metastasis through c-MET signaling." (PMID 41369362, 2025). "Additionally, in EGFR TKI-resistant breast cancer cell lines, the receptor tyrosine kinase MET plays a role in promoting resistance." (PMID 40560045, 2025). "In summary, these findings on CCL2/CCR2 and HGF/MET signaling in early-stage breast cancer could be used to tailor treatments for patients with DCIS." (PMID 40736024, 2025). "Similarly, MET overexpression is observed in many other cancers, including breast cancer (BC), where serum HGF levels increase with BC and are higher in patients with mBC." (PMID 40723207, 2025). "Thus, high levels of c-MET in breast cancer correlate with faster tumor growth, metastasis, tolerance to radiation therapy, and low overall survival." (PMID 39063041, 2024). "In addition, recent studies from our lab demonstrated remarkable synergistic anticancer activity for the combination of crizotinib, a MET inhibitor, with the endocrine drugs tamoxifen and fulvestrant in different breast cancer cell lines in vitro." (PMID 39742369, 2024). "PIK3CA and c-MET are often co-altered across various cancer types, including breast cancer." (PMID 39769140, 2024). "Additionally, a therapeutic humanized anti-β1 neutralizing antibody inhibited MET-β1 interaction in breast cancer cells, further reducing cell motility and invasion." (PMID 39769452, 2024). "Specifically, they demonstrated that overexpression of Thymocyte Expressed Molecule Involved In Selection 2 (THEMIS2) in breast cancer promotes the binding of Protein-Tyrosine Phosphatases 1B (PTP1B) to MET, leading to MET activation, and ultimately sustaining stemness characteristics." (PMID 38965243, 2024). "MET plays a role in Tmab resistance in HER2-positive breast cancer (BC) cells." (PMID 38892160, 2024).
breast carcinoma (continued). "Interestingly, apart from LC (2 events), fusions with CFTR were detected in 1 GEC and 1 breast cancer case in the forms of MET‐CFTR and CFTR‐MET, respectively." (PMID 37326363, 2023). "However, miR-200a-5p has the opposite effect in breast cancers as suppresses cell proliferation by regulating the expression of hepatocyte growth factor (MET) and epidermal growth factor receptor (EGFR)." (PMID 36991314, 2023). "However, MET mutation and amplification are rare events (around 1%) in breast cancer patients, while MET protein is commonly overexpressed in breast cancer tissues and brain metastatic samples." (PMID 37174093, 2023). "In addition, discovery of a novel interaction partners including Kunitz-type protease inhibitor SPINT2, pointed to the novel mechanism of tumor suppressor role of COMT in ER dependent breast cancer through the interplay with MET signaling pathway." (PMID 36690660, 2023). "A recent study in preclinical breast cancer models provided evidence that a combination of pan-HER inhibitors with MET inhibitors (including tepotinib) may help overcome HER2 inhibitor resistance among patients with cooperating pan-HER and MET dysregulation." (PMID 36999986, 2023). "COMT might act as an anti-invasive agent on ER + breast cancer also through its newly discovered interplay with MET signaling via its interacting partner, SPINT2, leading to the inhibition of this pro-tumorigenic pathway." (PMID 36690660, 2023). "The MET oncogene, encoding the tyrosine kinase receptor for a hepatocyte growth factor (HGF), plays a key role in the onset and progression of aggressive forms of breast cancer." (PMID 36139568, 2022). "In addition, c-MET is overexpressed in various cancers, including lymphoma, melanoma, glioma, breast cancer, pancreatic cancer, colorectal cancer, and ovarian cancer." (PMID 35630066, 2022). "Indeed, decorin binds VEGFR2 expressed by the endothelial cells and MET that abundantly (that is, target-rich) adorns breast cancer cells." (PMID 35159071, 2022). "Cooperation of MET inhibitors with PARPi has been reported in breast cancer cell lines exposed to hypoxia that resulted in MET activation and nuclear transport where it could phosphorylate PARP1 directly." (PMID 35628590, 2022). "In addition to breast cancer, c-MET/p-Y907 PARP axis meditated PARPi resistance has also been demonstrated in other cancer types, including ovarian and pancreatic cancer." (PMID 36284291, 2022). "Interestingly, the growth of tumour xenografts formed by ABCB1/MDR1-overexpressed MDR uterine sarcoma and breast cancer cell lines, knocked down for MET with shRNA, was reduced compared to tumours formed by control shRNA transfected cells." (PMID 33526881, 2021). "Indeed, activation of c-MET signaling in breast cancer cells promotes metastasis of breast cancer cells and secretion of HGF from tumor-associated astrocytes in the brain." (PMID 34439392, 2021). "More specifically, a hypo-methylated L1PA2 transposon is found to act as an alternate promoter to the MET oncogene in breast cancer, chronic myeloid leukemia and colorectal cancer, and the L1PA2-MET expression is associated with enhanced malignancy and poor prognosis." (PMID 33850167, 2021). "Moreover, c-MET has been found to be upregulated and in an activated state upon hypoxic conditions mediated by VEGFR inhibitors and pericyte loss in breast cancer models, including the 4T1 fat pad model." (PMID 33731699, 2021). "The effect of the HGF/MET signaling pathway on breast cancer cells requires the presence of SIPA1." (PMID 33917539, 2021). "The dual MET/ALK inhibitor crizotinib showed a dose-dependent reduction of viability in various breast cancer cell lines after 48 h of treatment, with an IC50 of 5–10 μM18, which is similar to the IC50 obtained in our HGF-stimulated, crizotinib-treated chordoma cells." (PMID 34127734, 2021).
breast carcinoma (continued). "Moreover, Verma and colleagues demonstrated that MET-mediated activation of Pyk2 contributes to metastasis of breast cancer." (PMID 33898310, 2021). "Copy number (CN) alterations in ctDNA were also associated with breast cancer subtype, with CN alterations in MYC, PIK3CA, EGFR, CCNE1, CDK6, BRAF and MET more common in TNBC (q = 0.01, q < 0.0001, q = 0.001, q < 0.0001, q = 0.0003, q = 0.0002 and q = 0.01, respectively)." (PMID 33893289, 2021). "The remarkable difference in the prognostic value of HGF and c-MET compared to female breast cancer might result from differences in tumor and environment biology between male and female breast cancer." (PMID 32188473, 2020). "Wu and Breunig confirmed the hypothesis of post-transcriptional regulation of MET by revealing that miR-340 and miR-128-3p negatively regulate MET expression, thus inhibiting the invasion and migration of breast cancer cells." (PMID 32083078, 2020). "However, MET amplification appears at a very low percentage in different breast cancer data sets both in primary (TCGA BRCA (0.4%), (1.5%), (0.1%)) and metastatic tumours (2.3%), MBC project 2018 (1.3%), (0.2%), (0.15%)." (PMID 32030896, 2020). "We found that MET downregulated both the proliferation and viability of breast cancer cells." (PMID 33108409, 2020). "In breast cancer, MET and ERBB2 are also coexpressed and related to therapeutic resistance." (PMID 33204717, 2020). "Besides breast cancer, a putative relationship between MET and TGFBR2 expression was observed also in cell lines from other tumor entities using the NCI‐60 as well as the 789 cell line panels of the NCI and the Sanger Institute, respectively." (PMID 30004628, 2018). "Similarly, miR-335 has been confirmed to inhibit the migration of cancer cells via binding c-MET mRNA in pancreatic and breast cancer." (PMID 30360560, 2018). "However, little is known about how MET expression is regulated downstream of TGFβ signaling in breast cancer." (PMID 30004628, 2018). "We could establish a positive correlation of TGFBR2 and MET protein expression in breast cancer by analyzing 801 tumor tissues samples." (PMID 30004628, 2018). "By revealing TGFβ1 as a regulator of HGF/MET‐induced cell migration, our findings suggest TGFβ1 with its downstream mediators C‐ets‐1 and miR‐128‐3p as potential targets for therapy of basal‐like breast cancer." (PMID 30004628, 2018). "Similarly, tumors deriving from cells that physiologically express MET, including glioblastomas and breast carcinomas, can acquire anomalous HGF expression." (PMID 30544501, 2018). "Hence, we define TGFβ1 as a regulator of MET expression in breast cancer by upregulating C‐ets‐1 and downregulating miR‐128‐3p expression, which results in cell migration, invasion, and metastasis in a HGF‐dependent manner." (PMID 30004628, 2018). "Based on previous studies, we hypothesized that we can decrease the expression of AXL and MET simultaneously by overexpressing miR-34a in breast cancer cell lines." (PMID 30386383, 2018). "Previous studies highlight the role of AXL and MET in breast cancer." (PMID 30386383, 2018). "Expression of MET is elevated in basal‐like tumors and inflammatory breast carcinoma; however, it is still not fully understood how MET is regulated in breast cancer cells." (PMID 30004628, 2018). "Next, we investigated whether the expression of MET is related to specific breast cancer subtypes and therefore checked its differential expression in cell lines of different breast cancer subtypes." (PMID 30004628, 2018). "MET expression correlates positively with EGFR expression in basal-type breast cancers." (PMID 30227653, 2018). "In the previous cases (with and without treatments), we have considered that metastases in the bone are originated only by breast cancer cells with four driver mutations relative to four proteins EPCAM, CD44, CD47 and MET, and they correspond to four branching of the CTCs departing from the DLU." (PMID 25978366, 2015).
breast carcinoma (continued). "Interestingly, data suggest that hepatocyte growth factor (HGF), the ligand for MET, and MET are expressed to a greater degree in triple-negative breast cancer relative to other breast cancer subtypes." (PMID 26123926, 2015). "ADSCs increase HGF production in presence of c-MET positive primary breast cancer cells, which in turn increase their HGF production; this observation confirms that the stroma creates a microenvironment where cancer cells are continuously stimulated to proliferate." (PMID 28536400, 2015). "Using breast cancer cell lines, studies showed that Erk5 plays roles in cell proliferation by regulating cyclin D1 and CDKs, epithelial mesenchymal transition, MET/HGF-induced migration and integrin/FAK-mediated metastasis." (PMID 24762669, 2014). "Importantly, activators of c-MET are secreted by adipose-derived mesenchymal stem cells, which exacerbate oncogenic behaviour of c-Met-expressing breast cancer cells, creating an inflammatory microenvironment, thus increasing tumor growth and angiogenesis." (PMID 24727648, 2014). "Overexpression of MET has been found in tissues derived from breast cancer patients." (PMID 23601074, 2013). "Altogether our previously published data strongly suggest that targeting MET,might have a therapeutic value in the treatment of bone metastases from breast cancer." (PMID 24260160, 2013). "Given the high expression of wound response genes in the tissue adjacent to cancer and the important role of HGF in normal ductal morphogenesis and invasive breast cancer, a better understanding of HGF/MET in progression of basal-like breast cancers is important." (PMID 24025166, 2013). "However, in this study, a cell line was used as a simplified model to testify the effect of NaBu and c-MET on breast cancer." (PMID 22253909, 2012). "c-MET attenuates the apoptosise effect induced by NaBu in breast cancer cells." (PMID 22253909, 2012). "Interestingly, MET activation has already been described for a pericyte-depleted mouse model of breast cancer, and poor pericyte coverage in combination with high MET expression has been identified as a predictor of poor outcome in patients with invasive breast cancer." (PMID 41339360, 2025). "The association of RON with MET and EGFR has been investigated by immunoprecipitation and cross-linking experiments, demonstrating receptor transphosphorylation, which may play a role in predicting therapeutic response and drug resistance in breast cancer." (PMID 40560045, 2025). "Interestingly, targeting of CCR2 and MET resulted in the highest reduction in growth of mammary carcinomas, corresponding to a significant increase in cancer cell apoptosis, decreased cellular proliferation, as well as reduced stromal reactivity and inflammation in the microenvironment." (PMID 40736024, 2025). "Moreover, integrating proteomic analyses with genomic data could provide a more comprehensive understanding of the role of ERs and MET protein levels and their functional interactions in breast cancer." (PMID 39742369, 2024). "Hence, our results should be interpreted with caution, acknowledging that mRNA expression may not fully capture the complex regulation and activity of ERs and MET in breast cancer." (PMID 39742369, 2024). "Finally, the authors suggested that modulating ATF3 expression or its downstream targets, such as MET, might be a potential therapeutic method for breast cancer therapy, especially in patients with severe metastatic illness." (PMID 38046946, 2023). "Concurrent with the view that MET proteolysis likely results from an intrinsic cellular mechanism that attenuates excessive MET signaling, it was shown that MET ectodomain shedding augments with increased malignant potential by taking advantage of an in vitro derived breast cancer progression model." (PMID 35326642, 2022).
breast carcinoma (continued). "On the one hand, induction of PD-L1 expression in tumor cells may increase the sensitivity of cancer cells to PD-1/PD-L1 immune checkpoint blockade, such as Poly-(ADP-ribose) polymerase (PARP) inhibitors in breast cancer and MET proto-oncogene, receptor tyrosine kinase (MET) inhibitors in HCC." (PMID 35907881, 2022). "Therefore, it was suggested that the overexpression of the MET cytoplasmic tail may favor breast cancer progression upon proteolytic cleavage or by truncating mutations." (PMID 35326642, 2022). "In addition, abnormal c-MET expression in several carcinomas, including breast cancer, cervical cancer, gastric cancer, and colorectal cancer, produces several signaling cascades and is associated with enhanced proliferation, blocking apoptosis, and poor prognosis." (PMID 35630066, 2022). "Besides, OLE has been able to reduce c-MET kinase activity, cell growth, and the migration and invasion of breast cancer cells; induce G1 cell cycle arrest and apoptosis; as well as inhibit c-MET-dependent signaling in cultured breast cancer cells and tumorigenicity in in vivo murine models." (PMID 32050687, 2020). "However, whether the CXCL12/CXCR4 and the HFG/c-MET axis hold similar significance in male breast cancer is unknown." (PMID 32188473, 2020). "In the first case, mutations occur in the extracellular SEMA domain, likely affecting the ligand–receptor interaction or the ability of MET to dimerize, and have been detected in lung, gastric, and breast cancer, as well as in cancers of unknown primary (CUPs)." (PMID 30544501, 2018). "Similarly, the HGF produced by adipose-derived stem cells (ASCs), together with the c-MET expressed in primary breast carcinoma cells, increases tumor cell migration, metastasis and self-renewal through PI3K-mediated GS3K inactivation and β-catenin stabilization and nuclear accumulation." (PMID 30352967, 2018). "In addition, optimal efficacy has been observed when Notch pathway inhibitors are combined with HER2 inhibitors in HER2-positive breast cancer, with endocrine therapy in ER-positive breast cancer, and with taxanes and MET inhibitors in triple-negative breast cancer." (PMID 27793013, 2017). "Moreover, the significant antitumor efficacy of new tyrosine kinase inhibitor (TKI) XL-184 (cabozantinib maleate), which targets MET and VEGFR-2, for bone metastasis in patients with prostate or breast cancers also shows the importance of HGF/MET signaling in bone metastasis." (PMID 25186085, 2015). "In a small study comprised of 11 patients with breast cancer (including six patients that showed loss of heterozygosity in the region of the MET gene), no mutations in the tyrosine kinase domain of the MET were identified, suggesting that this is not a common event in breast cancer." (PMID 25887320, 2015). "Thus the oncogene MET helps breast cancer line survival through the treatment of NaBu." (PMID 22253909, 2012). "The cross-talk between mesenchymal-epithelial transition factor (c-MET) and epidermal growth factor receptor (EGFR) plays a role in breast cancer (BC) progression and resistance to various targeted therapies." (PMID 41234389, 2025). "The unique and aberrant overexpression and/or activation profiles of RTKs in breast cancers, particularly HER2, hepatocyte growth factor receptor (MET), and EGFR, make them promising prognostic markers and therapeutic targets for disease management." (PMID 40560045, 2025). "Overall, these studies provide insight into how CCL2 and HGF function to coordinate breast cancer growth, survival, invasion, and metabolism, and demonstrate that targeting CCR2 and MET inhibit DCIS progression." (PMID 40736024, 2025). "Blocking the MUC5AC/c-MET/CD44v6 complex with a blood–brain barrier-permeable c-MET inhibitor, bozitinib, effectively reduces MUC5AC expression and decreases the metastatic potential of breast cancer cells to the brain." (PMID 41369362, 2025).